NGB (neuroglobin)
Description:
Monomeric globin with a bis-histidyl six-coordinate heme-iron atom through which it can bind dioxygen, carbon monoxide and nitric oxide. Could help transport oxygen and increase its availability to the metabolically active neuronal tissues, though its low quantity in tissues as well as its high affinity for dioxygen, which may limit its oxygen-releasing ability, argue against it. The ferrous/deoxygenated form exhibits a nitrite reductase activity and it could produce nitric oxide which in turn inhibits cellular respiration in response to hypoxia. In its ferrous/deoxygenated state, it may also exhibit GDI (Guanine nucleotide Dissociation Inhibitor) activity toward heterotrimeric G-alpha proteins, thereby regulating signal transduction to facilitate neuroprotective responses in the wake of hypoxia and associated oxidative stress.
Tractability: Small molecule: a structure with a bound ligand is known.
Gene: Protein-coding gene on chromosome 14 (77,265,483 to 77,271,206, reverse strand). Ensembl gene ENSG00000165553.
Subcellular location: Cytoplasm, cytosol; Mitochondrion matrix
Subcellular location (Human Protein Atlas): Cytosol
Pathways (Reactome):
Transport of small molecules: Intracellular oxygen transport
Gene Ontology:
Molecular function: GDP-dissociation inhibitor activity; nitrite reductase activity; oxygen binding; protein binding; oxygen carrier activity; heme binding
Biological process: cellular response to hypoxia; oxygen transport; response to hypoxia
Cellular component: cytosol; mitochondrial matrix
Genetic constraint (gnomAD): Loss-of-function variants: 10 observed, 11.64 expected, observed/expected ratio (o/e) 0.86, 90% interval 0.53 to 1.45. The upper end of that interval is the gene's LOEUF score, 1.45, which puts it in group 6 of 6, group 1 being the genes least tolerant of losing a copy. Missense variants: 188 observed, 167.46 expected, observed/expected ratio (o/e) 1.12, 90% interval 1 to 1.27. Synonymous variants: 82 observed, 66.52 expected, observed/expected ratio (o/e) 1.23, 90% interval 1.03 to 1.48.
Homologues: Orthologues: chimpanzee NGB (100% identical), macaque NGB (99% identical), pig NGB (96% identical), dog NGB (95% identical), guinea pig NGB (95% identical), mouse Ngb (94% identical), rat Ngb (93% identical), tropical clawed frog ngb (62% identical), zebrafish ngb (53% identical).
Diseases named in the same sentence as NGB in open-access papers:
NGB is named in the same sentence as 73 diseases in open-access papers, as found by Europe PMC text mining. Sharing a sentence is not in itself a finding about the gene and the disease. The quoted sentences say what the papers report.
Stroke (21 papers, 2010 to 2026). Sudden impairment of blood flow to a part of the brain due to occlusion or rupture of an artery to the brain. "In conclusion, the systemic administration of neuroglobin linked to nanoparticles is a potential neuroprotective drug-delivery strategy after stroke episodes." (PMID 31947806, 2020). "In one of the first population level studies involving neuroglobin no mutant forms of the coding region of neuroglobin was found, but polymorphism in the first intronic region of the neuroglobin gene was shown to be associated with a decreased risk of stroke in the Han Chinese population." (PMID 24710547, 2012). "Neuroglobin (Ngb) is an endogen neuroprotective protein, but it only exerts its beneficial action against stroke after increasing its basal levels." (PMID 36015363, 2022). "The Wnt signalling pathway mediates the neuroprotective effects of neuroglobin (Ngb) by promoting neurogenesis in certain neurodegenerative conditions such as stroke." (PMID 35291879, 2022). "In this work, these nanoparticles have been used to carry neuroglobin through the bloodstream to the nerve cells in rats submitted to stroke." (PMID 31947806, 2020). "The neuroglobin protein plays an important role in the neuro-regeneration process after stroke; however, the method for its effective systemic application has not been identified yet, as neuroglobin is unable to pass through the blood-brain barrier." (PMID 31947806, 2020). "Overall, the pharmaceutical formulation developed in this study is a delivery system that can successfully carry the neuroprotective oxygen-sensing protein NGB to the damaged ischemic brain after stroke." (PMID 31947806, 2020). "Neuroglobin (Ngb) is an endogenous neuroprotectant with hypoxia-inducible property, and its role in experimental stroke has been increasingly attractive." (PMID 29802248, 2018). "Neuroglobin (Ngb) has been demonstrated by our lab and others to be neuroprotective against neurological disorders including stroke." (PMID 30237546, 2018). "Neuroglobin (Ngb) is an oxygen-binding globin protein that has been demonstrated to be neuroprotective against stroke and related neurological disorders." (PMID 23634236, 2013). "Neuroglobin, a neuronal heme-globin, has been advocated as a novel pharmacological target in combating stroke and neurodegenerative disorders based on cytoprotective properties." (PMID 24098534, 2013). "The area of targeting endogenous neuroglobin for the protection against stroke and neurodegenerative disorders has recently been reviewed." (PMID 24710547, 2012). "17β estradiol has also shown promise in the upregulation of neuroglobin and in fact has been known to be protective against stroke in post-menopausal women in for some time." (PMID 24710547, 2012). "In humans neuroglobin appears up regulated following stroke, Alzheimer’s and glaucoma and is over expressed in some tumors." (PMID 24710547, 2012). "Following on from their initial work on cells and model systems the groups of Greenberg and Wang have gone on to establish the significance of neuroglobin in situations of stroke, cerebral ischemia and intracerebral hemorrhage." (PMID 24710547, 2012). "Neuroglobin is considered to be a novel important pharmacological target in combating stroke and neurodegenerative disorders, although the mechanism by which this protection is accomplished remains an enigma." (PMID 22901501, 2012). "Increased expression of neuroglobin has been shown to protect against stroke and Alzheimer’s disease in vivo, and to promote neural survival after oxygen or glucose deprivation, or following oxidative stress." (PMID 20640154, 2010). "It has been shown that this compound could be a prominent alternative for stroke treatment by interacting and activating neuroglobin." (PMID 36675984, 2022).
Stroke (continued). "Accumulating evidence has demonstrated that the oxygen-binding neuroglobin protein (NGB), acts as a neuroprotective molecule against stroke in humans, and against some hypoxic/ischemic (H/I), and oxidative stress-related insults in animals and cultured neurons." (PMID 31947806, 2020). "Therefore, there is an increasing interest in using potentially neuroprotective endogenous expressed proteins as targets for pharmacological stroke treatment, Neuroglobin (Ngb) being one of them." (PMID 24098534, 2013). "In animal models over-expression of neuroglobin protects against stroke and brain injury." (PMID 24710547, 2012). "Neuroglobin is found in high concentration in some neurons, and its high expression has been shown to promote survival of neurons in vitro and to protect brain from damage by both stroke and Alzheimer’s disease in vivo." (PMID 20640154, 2010). "For the treatment of stroke in chronic convalescence, reports have clarified that LRIC can promote the recovery of neurologic function by promoting arteriogenesis and increasing neuroglobin." (PMID 36009031, 2022). "In NGB-transgenic mice, NGB overexpression with more than 2.7-fold protein level increase driven by CMV promoter or by chicken β-actin promoter ameliorated the severity of histological and functional deficits in stroke models." (PMID 27809238, 2016). "Moreover, various potential functions of neuroglobin (NGB) have been exhibited and found to be able to reduce the severity of stroke and AD." (PMID 24367332, 2013). "As in the case of Hb, the potency and efficacy of others oxygen-binding globins, neuroglobin, and myogolobin, in preventing neuronal cell death have been proven against various neurotoxins, including H2O2, and brain injuries induced by hypoxia, ischemia, or stroke." (PMID 28443065, 2017). "However, in a cellular stroke model, based on oxygen /glucose deprivation in CHO and SHY5Y cells, no protective effect was evident for the TAT-neuroglobin fusion protein." (PMID 24710547, 2012).
breast carcinoma (15 papers, 2014 to 2026). "In all the analyzed proteomes, cytoskeletal proteins were found to be subjected to quantitative variation (mostly being downregulated) as a common feature of NGB-deficient breast cancer cells." (PMID 33924212, 2021). "For example, NGB encodes for an anti-apoptotic neuroglobin protein which acts as a sensor of oxidative stress, hypoxia, and nutrient deprivation in breast cancer cells." (PMID 32051475, 2020). "The results reported here showing the association between NGB accumulation and ERα+ ductal carcinoma tissues could sustain the promise of improving prognostication and treatment decisions for breast cancer patients." (PMID 34440755, 2021). "Here, we report for the first time a proteomic survey in NGB-deficient human breast cancer cells." (PMID 33924212, 2021). "In addition, E2-induced high intracellular NGB levels are at the root of the reduced susceptibility of ERα+ breast cancer cells to chemotherapeutic drugs." (PMID 32872414, 2020). "We previously demonstrated that several E2-induced actions in ERα-positive breast cancers strongly rely on the activation of a specific E2/ERα/Neuroglobin (NGB) axis, leading to NGB accumulation and its mitochondrial location." (PMID 36768470, 2023). "We previously demonstrated that the ERα/NGB pathway is a compensatory mechanism triggered by E2 to increase the survival of breast cancer cells against different stressors, including chemotherapeutic drugs." (PMID 36768470, 2023). "On this premise, a concentration of 9.1 μg/mL, corresponding to an RSV load of 0.1 μM, was indicated as safe and used to evaluate NGB modulatory action on breast cancer cells expressing different ERα levels." (PMID 36768470, 2023). "Human MCF-7 breast cancer cells with a knocked-out (KO) NGB gene obtained using CRISPR/Cas9 technology were analyzed using shotgun label-free quantitative proteomics in comparison with control cells." (PMID 33924212, 2021). "Mitochondrial accumulation of NGB in breast cancer cells counteracts the trigger of apoptosis induced by oxidative stress." (PMID 33924212, 2021). "Consistent with this, our previous data define NGB accumulation as the key factor in the E2-activated ERα pathway devoted to breast cancer cell survival against oxidative stress and chemotherapeutic agents." (PMID 34440755, 2021). "In the scenario of a possible correlation between globins function in breast cancer cells, the data of an opposite link between the MB expression or NGB levels (, and results reported here) and ERα activation is particularly interesting." (PMID 34440755, 2021). "By using the GOBO data set, we analyzed the possible association between NGB gene (ID = 58157) expression levels with Overall Survival (OS) and Relapse-Free Survival (RFS) outcomes in G1, G2, and G3 subgroups of ERα+ breast cancer data set." (PMID 34440755, 2021). "In line with previous results obtained in breast cancer cells, high levels of NGB have been detected only in tumor samples versus their matched normal tissue, sustaining a key role of the globin in breast cancer pathophysiology." (PMID 34440755, 2021). "On the other hand, the intracellular NGB can take part in the regulation of breast-cancer-dependent shaping of the extracellular milieu in response to external stimuli." (PMID 33924212, 2021). "The presence of high NGB levels in the highest-grade breast cancers can explain, at least in part, their bad prognosis." (PMID 34440755, 2021). "Our previous data identified the ERα/AKT/neuroglobin (NGB) pathway as a common pro-survival process activated in different ERα breast cancer cell lines." (PMID 34440755, 2021). "For this purpose, we utilized two human ERα positive breast cancer cells in which the pathway E2/ERα/NGB has been previously identified as pivotal for breast cancer cell susceptibility to the chemotherapeutic agent paclitaxel." (PMID 31936631, 2020).
breast carcinoma (continued). "Previous results indicated that NGB intracellular levels and localization are positively modulated in a panel of ERα+ breast cancer cells (MCF-7, ZR-751, T47D) either by E2, oxidative stress (H2O2), and reactive oxygen species (ROS)-inducing compounds." (PMID 32872414, 2020). "E2-induced NGB upregulation in cancer cells represents an inducible defense mechanism of E2-related human breast cancer rendering them insensitive to several injury including chemotherapy." (PMID 31936631, 2020). "As a whole, we shed new light on NGB indicating a new function as autocrine/paracrine factor in breast cancer." (PMID 32872414, 2020). "In particular, we recently demonstrated that E2 stimulation rapidly enhances the ERα activity (Ser118 phosphorylation and PI3K/AKT pathway activation) in breast cancer cells increasing the intracellular levels of an anti-apoptotic globin, neuroglobin (NGB)." (PMID 31936631, 2020). "A great amount of globin co-localizes with collagen fibers, suggesting that NGB can be released by breast cancer cells in vivo." (PMID 32872414, 2020). "The obtained data prompted us to evaluate the possible effects of extracellular NGB on breast cancer cells, mainly focusing on cell adaptation to oxidative stress, survival, and migration." (PMID 32872414, 2020). "In estrogen receptor α-positive breast cancer cells treated with D and its metabolites, single or in mixture, ERα activation and Neuroglobin (NGB) levels, an anti-apoptotic estrogen/ERα-inducible protein, were evaluated." (PMID 31936631, 2020). "Data reported indicate the presence of NGB in the extracellular matrix of breast cancer sections derived from human patients with ERα+ Grade 2 ductal carcinoma." (PMID 32872414, 2020). "In this context, we recently confirmed NGB as a stress-inducible protein in breast cancer cells, where it acts as a sensing and compensatory protein activated in response to oxidative stress." (PMID 31354909, 2019). "Our latest results support a critical role of NGB as cytosolic signals intermediate in breast cancer cell stress response, taking part in the E2-dependent activation of the NRF-2 pathway and potentiation of the antioxidant system." (PMID 31354909, 2019). "Intriguingly, E2 upregulates NGB in diverse breast cancer cell lines (MCF-7, T47D, and ZR-75-1) expressing just the subtype α of the estrogen receptor (ERα), but not in the ERα-devoid MDA-MB-231 cell line." (PMID 31354909, 2019). "Remarkably, as for neuron-derived cells, we demonstrated that NGB is a stress-inducible protein in breast cancer lines being upregulated in response to the oxidative stress, although low levels of O2 are unable to impact on the NGB expression." (PMID 29216269, 2017). "The effects of nutrient deprivation on the expression of NGB levels has been evaluated in human neuroblastoma cells (SK-N-BE), breast cancer cells (MCF-7) and the ER devoid HEK-293 stable transfected with ERα plasmid (ERα-HEK-293)." (PMID 29216269, 2017). "Data obtained in neuroblastoma and in breast cancer cell lines evidence that nutrient deprivation significantly up-regulated NGB levels at different time points." (PMID 29216269, 2017). "Results reported here clearly indicate that culturing cells in starved condition positively modulates NGB protein levels in both neuroblastoma and breast cancer cell lines." (PMID 29216269, 2017). "Here, we investigated the putative role of endogenous level of NGB in breast cancer cells as a stress sensor and as a compensatory protein, which responds to the injuring stimuli inhibiting the trigger of mitochondria-dependent apoptosis." (PMID 27149623, 2016). "Furthermore, RSV regulates the E2/ERα/NGB signaling pathway, microRNAs, and the Notch pathway to inhibit breast cancer cell proliferation." (PMID 39439517, 2024). "Furthermore, Res at low concentrations (10~7, 10−6, and 10~5 M) reduced NGB basal levels in ERα-positive breast cancer cells, specifically by antagonizing E2 effects." (PMID 36982977, 2023).